FCN2 (ficolin 2)
Description:
Calcium-dependent lectin, which acts as a pattern recognition receptor that initiates the lectin pathway of the complement system, a cascade of proteins that leads to phagocytosis and breakdown of pathogens and signaling that strengthens the adaptive immune system. Specifically recognizes and binds carbohydrates on the pathogen surface, activating the MASP1 serine protease and initiating the proteolytic cascade of the lectin complement pathway. Specifically binds N-Acetylglucosamine (GlcNAc), as well as phosphocholine and lipoteichoic acid moieties on the surface of pathogens. Enhances phagocytosis of S.typhimurium by neutrophils, suggesting an opsonic effect.
Synonyms: EBP-37; FCNL; P35; ficolin-2
Tractability: Small molecule: a structure with a bound ligand is known; it has a high-quality binding pocket. Antibody: its Gene Ontology location is reachable by antibodies, with high confidence; UniProt places it where antibodies can reach, with medium confidence; UniProt predicts a signal peptide or a membrane-spanning region.
Gene: Protein-coding gene on chromosome 9 (134,880,714 to 134,890,508, forward strand). Ensembl gene ENSG00000160339.
Subcellular location: Secreted; Cell surface
Pathways (Reactome):
Immune System: Ficolins bind to repetitive carbohydrate structures on the target cell surface; Initial triggering of complement; Lectin pathway of complement activation
Gene Ontology:
Molecular function: antigen binding; calcium-dependent protein binding; carbohydrate derivative binding; lipoteichoic acid immune receptor activity; mannan binding; pattern recognition receptor activity; protein binding; proteoglycan binding; signaling receptor binding
Biological process: complement activation, lectin pathway; defense response to Gram-negative bacterium; defense response to Gram-positive bacterium; opsonization; positive regulation of opsonization; proteolysis; recognition of apoptotic cell; cell surface pattern recognition receptor signaling pathway
Cellular component: blood microparticle; cell surface; extracellular exosome; extracellular region; serine-type endopeptidase complex; symbiont cell surface; external side of plasma membrane; extracellular matrix
Genetic constraint (gnomAD): Loss-of-function variants: 30 observed, 34.84 expected, observed/expected ratio (o/e) 0.86, 90% interval 0.64 to 1.17. The upper end of that interval is the gene's LOEUF score, 1.17, which puts it in group 5 of 6, group 1 being the genes least tolerant of losing a copy. Missense variants: 408 observed, 416.85 expected, observed/expected ratio (o/e) 0.98, 90% interval 0.9 to 1.06. Synonymous variants: 181 observed, 169.03 expected, observed/expected ratio (o/e) 1.07, 90% interval 0.95 to 1.21.
Homologues: Orthologues: chimpanzee FCN2 (98% identical), pig FCN2 (76% identical). Paralogues in human: FCN1 (80% identical), FCN3 (46% identical), TNC (46% identical), TNXB (45% identical), TNR (44% identical), TNN (42% identical), FIBCD1 (37% identical), FGB (34% identical), MFAP4 (34% identical), ANGPTL2 (34% identical), ANGPTL7 (33% identical), ANGPT1 (32% identical), and 13 more.
Diseases named in the same sentence as FCN2 in open-access papers:
FCN2 is named in the same sentence as 128 diseases in open-access papers, as found by Europe PMC text mining. Sharing a sentence is not in itself a finding about the gene and the disease. The quoted sentences say what the papers report.
leprosy (10 papers, 2012 to 2024). Leprosy is a chronic infectious disease affecting primarily the skin and peripheral nervous system. "As with FCN2 polymorphisms, the association was restricted to leprosy patients with a dominant effect, meaning that heterozygote individuals are already at higher risk." (PMID 33643280, 2020). "In previous studies, we demonstrated that FCN2 gene haplotypes associated with normal ficolin-2 levels have a protective effect against leprosy and that FCN1 gene -271DelT, -399A, -542G, -1981A polymorphisms were associated with susceptibility to leprosy." (PMID 28241035, 2017). "Specific FCN2 haplotypes associated with normal L-ficolin levels seemed to be protective against clinical leprosy." (PMID 23533355, 2013). "This group also found that FCN2 was associated with Brazilian leprosy patients." (PMID 32373110, 2020). "However, previous research on the association between the FCN2 gene and leprosy has shown that the frequency of -557 A>G GG genotype in patients with leprosy was not significantly different (P = 0.085) compared to the healthy controls." (PMID 26379154, 2015). "Also recent studies have investigated the possible associations between FCN2 gene polymorphisms to ficolin-2 levels in rheumatic fever, rheumatic heart disease, leprosy, hepatitis B virus and malaria." (PMID 22457818, 2012). "Another GWAS study has confirmed the association of complement genes FCN2, MBL2, and CFH with leprosy susceptibility." (PMID 38440733, 2024). "One study showed that the functional haplotypes that produce serum FCN2 eliminate M. leprae via mononuclear phagocytes and protect subjects against leprosy." (PMID 35622698, 2022). "These two findings were subsequently confirmed by a candidate loci association study using Han Chinese, in which the authors found that genetic variants of FCN2 and MBL2 genes conferred susceptibility to leprosy." (PMID 32373110, 2020). "The frequency of +6424 G>T TT genotype also showed different function of FCN2 between pulmonary TB and paucibacillary leprosy." (PMID 26379154, 2015). "Based on this, relevant therapeutic and prevention strategies may include enhancing the activity of FCN2 to improve the recognition and clearance of leprosy pathogens." (PMID 38440733, 2024). "Regarding FCN2 promoter-exon 1 haplotypes, those two sharing the first three 5′ rs3124952*G, rs3124953*G, and rs3811140*G (GGG) variants were also associated with increased susceptibility to leprosy/HBV infection (OR = 2.6 [95%CI = 1.13–5.96], P = 0.034)." (PMID 33643280, 2020). "Furthermore, FCN2 and FCN1 haplotypes have protective effects against the susceptibility to leprosy per se." (PMID 28241035, 2017). "Functional haplotypes that produce normal ficolin-2 levels protect against clinical leprosy." (PMID 26379154, 2015). "There were no FCN2 or FCN3 haplotypes associated with HBV infection although we confirmed the protective association of the FCN2 promoter-exon 1 haplotype AGAAAC with leprosy per se (OR = 0.13 [95%CI=0.02–0.99], p = 0.018)." (PMID 33643280, 2020). "The frequencies of TA haplotypes (composed by rs17549193 and rs7851696 encoding the ancestral amino acids threonine at position 236 and alanine at position 258 of the ficolin-2 protein, respectively) were higher among HBV+ than among HBV− leprosy patients (OR = 2.19 [95%CI = 1.14–4.23], P = 0.022)." (PMID 33643280, 2020).
hepatocellular carcinoma (6 papers, 2020 to 2024). A malignant tumor that arises from hepatocytes. "FCN2 inhibits epithelial-mesenchymal transition-induced metastasis of hepatocellular carcinoma via TGF-β/Smad signaling." (PMID 38698462, 2024). "Considering that response to infection decreases during aging and hepatocellular carcinoma is also an age-related disease, our findings with regard to FCN2 is of potential relevance." (PMID 37239116, 2023). "Overexpression of FCN2 inhibits hepatocellular carcinoma through the TGF-β signaling pathway." (PMID 39739972, 2024). "Furthermore, FCN2 may suppress hepatocellular carcinoma migration and invasion, as demonstrated by a study conducted on mice." (PMID 37239116, 2023). "Correlation analysis between FCN2 and the biomarkers of immune cells in hepatocellular carcinoma (HCC) determined using the GEPIA database (Spearman’s correlation coefficient)." (PMID 36425563, 2022). "This study aimed to investigate the role of ficolin-2 (FCN2) in the development and course of hepatocellular carcinoma (HCC) and to contribute to the evolution of innovative HCC therapeutics." (PMID 36425563, 2022). "Interestingly, serum ficolin-2 concentrations were higher in chronic HBV patients than in healthy controls and HBV carriers and decreased with positive treatment response, but was lowest in individuals with hepatocellular carcinoma and cirrhosis." (PMID 33643280, 2020). "However, previous studies have also shown that FCN2 and MBL can be used as biomarkers for the progression of chronic HCV infection to hepatocellular carcinoma, especially when the conversion from HCV to HCC is followed by a significant increase in FCN2 expression." (PMID 35928441, 2022).
bronchiectasis (5 papers, 2015 to 2023). Segmental, irreversible dilation of the bronchial tree resulting in the accumulation of secretions which leads to obstruction. "For example, relative ficolin-2 deficiency was shown to predispose to the development of bronchiectasis and to predict disease progression in patients with idiopathic pulmonary fibrosis." (PMID 36733481, 2023). "Common variable immunodeficiency (CVID) patients with bronchiectasis also demonstrate low levels of FCN2." (PMID 27490795, 2016). "Furthermore, FCN2-deficiency may predispose patients to development of bronchiectasis." (PMID 27490795, 2016). "Low ficolin-2 concentrations may be observed in patients with bronchiectasis and may facilitate their development." (PMID 34391418, 2021).
Cirrhosis (5 papers, 2011 to 2025). A chronic disorder of the liver in which liver tissue becomes scarred and is partially replaced by regenerative nodules and fibrotic tissue resulting in loss of liver function. "We measured four different PRMs (mannose-binding lectin [MBL], ficolin-1, ficolin-2 and ficolin-3) using stored sera, and retrospectively analyzed the associations between PRMs and laboratory findings, histological findings, and the development of cirrhosis-related conditions." (PMID 32915797, 2020). "One possible reason for decreased Ficolin- 2 levels in patients with liver cirrhosis is that during cirrhosis, the liver tissues are damaged and the blood circulation in the organ may be blocked and resulting in decreased Ficolin-2 production or a reduced secretion in the peripheral blood." (PMID 22140517, 2011). "Furthermore, Chen observed that intrahepatic expression and serum levels of FCN-2 were much lower in HCC and cirrhosis than in healthy controls." (PMID 35269955, 2022).
cutaneous leishmaniasis (5 papers, 2012 to 2021). Leishmaniasis affecting the skin. "In this study, we analyzed five functional polymorphisms of the FCN2 gene for their possible association with cutaneous leishmaniasis." (PMID 22457818, 2012). "We investigated the contribution of FCN2 functional variants in 226 patients with cutaneous leishmaniasis and 286 healthy controls from Syria." (PMID 22457818, 2012). "Genetic variations in both MBL and ficolin-2 have recently been associated with both visceral and cutaneous leishmaniasis." (PMID 23139754, 2012). "Our results demonstrate a significant association of FCN2 AGACG haplotype with cutaneous leishmaniasis in a Syrian Arab population." (PMID 22457818, 2012). "Genetic variants on the FCN2 gene have also been assessed for Cutaneous Leishmaniasis (CL)." (PMID 34899745, 2021). "Interestingly, a significant association of a distinct FCN2 haplotype with cutaneous leishmaniasis has been reported from a Syrian population." (PMID 25965808, 2015). "These first results provide a basis for a future study that could confirm or disprove possible relationships between FCN2 gene polymorphisms with cutaneous leishmaniasis." (PMID 22457818, 2012). "Although it has been showed that FCN2 gene polymorphisms and haplotypes are associated with cutaneous leishmaniasis, no investigations of ficolins have so far focused on VL." (PMID 25965808, 2015). "As observed from other studies, we do not observe a significant contribution of the FCN2 genotypes; however, we observed that the AGACG haplotypes contributed to increased susceptibility to cutaneous Leishmaniasis." (PMID 22457818, 2012).
malaria (5 papers, 2012 to 2025). Malaria is a serious and sometimes fatal disease caused by a parasite that commonly infects a certain type of mosquito which feeds on humans. "SNPs in FCN2 have also been reported to be correlated with a predisposition to parasitic infections, including, leishmaniasis, malaria, Chagas disease, and schistosomiasis." (PMID 30868077, 2019). "infections, showing ficolin-2 levels are associated with severe malaria." (PMID 40422078, 2025). "We measured ficolin-1 and ficolin-2 concentrations in plasma from Malawian children presenting with uncomplicated or severe malaria or healthy controls (HCs) by ELISA." (PMID 40422078, 2025). "In Gabonese children, concentrations of ficolin-2 were higher at presentation in children with severe malaria than in those with uncomplicated disease." (PMID 40422078, 2025). "This was surprising as ficolin-2 concentrations in plasma have previously been shown to be increased with infectious diseases including dengue and malaria." (PMID 40422078, 2025). "Unlike ficolin-1, we did not see associations between ficolin-2 concentrations and any of the two clinical types of malaria studied." (PMID 40422078, 2025). "Unlike with ficolin-1, we did not see a clear association between ficolin-2 concentrations and malaria." (PMID 40422078, 2025). "Whether ficolin-2 levels vary with malaria severity needs to be investigated further." (PMID 40422078, 2025). "To further understand whether ficolins play any role in the human immune response to malaria, we determined whether ficolin-1 and ficolin-2 concentrations varied with malaria disease and disease severity in plasma samples collected from children residing in a malaria endemic area." (PMID 40422078, 2025). "However, the data in the paper suggest that concentrations of ficolin-2 are not higher in those with severe compared to uncomplicated malaria, which contrasts with a previously published study." (PMID 40422078, 2025).
Sepsis (5 papers, 2015 to 2024). Sepsis is defined as life-threatening organ dysfunction caused by a dysregulated host response to infection. "Low ficolin-2 concentration in cord serum was also found associated with a higher risk of perinatal infections, including sepsis." (PMID 38193083, 2023). "Low (<1 μg/ml) ficolin-2 levels were found significantly more often in disease groups (babies with perinatal infections who developed sepsis or with milder disease course) compared with infection-free controls." (PMID 38193083, 2023). "Although no impact of the SNPs, haplo- or diplotypes investigated here on such adverse effects of prematurity as perinatal infections, sepsis, pneumonia or RDS was found, it does not exclude a possible influence of low ficolin-2 on such complications." (PMID 36499663, 2022).
systemic lupus erythematosus (5 papers, 2018 to 2025). An autoimmune multi-organ disease typically associated with vasculopathy and autoantibody production. "In a Danish study of patients with systemic lupus erythematosus, a complement-mediated autoimmune disease, low FCN2 levels, stratified by its median, predicted the development of lupus nephritis." (PMID 40342947, 2025).
tuberculosis (5 papers, 2012 to 2021). A chronic, recurrent infection caused by the bacterium Mycobacterium tuberculosis. "The association between ficolin-2 and tuberculosis as revealed by our results corroborates previous data that ficolin-2 insufficiency is associated with recurrent respiratory infections in children." (PMID 24040095, 2013). "Of course, it might be possible that other fatal diseases like tuberculosis exerts the selective force on the FCN2 polymorphisms and Leishmania profits from this selective process." (PMID 22457818, 2012). "The present study aimed to investigate the association of the FCN2 gene single nucleotide polymorphisms (SNPs) with susceptibility to pulmonary tuberculosis (TB)." (PMID 26379154, 2015). "Nevertheless, discordant results were reported for ficolin-2 in tuberculosis and Chagas disease, where cases presented lower ficolin-2 plasma levels than did controls." (PMID 25965808, 2015). "The time to 50% mortality (T50) was reached at more than 43 days for the ficolin-2-treated group and the group given seven successive injections (once per day) of streptomycin (SM), which is an antibiotic drug commonly used to treat tuberculosis." (PMID 24040095, 2013). "Ficolin-2 is an important lectin molecule in serum, and its reduction may contribute to the progression of tuberculosis." (PMID 24040095, 2013). "Here, we describe our novel findings that the ficolin-2 serum levels of 107 pulmonary tuberculosis (TB) patients were much lower compared with 107 healthy controls." (PMID 24040095, 2013). "Patients with tuberculosis have been reported to have lower ficolin-2 levels compared to healthy controls, and in vitro experiments have shown L-ficolin to bind to virulent mycobacteria more so than non-virulent mycobacteria." (PMID 33498555, 2021).
dengue (4 papers, 2021 to 2025). "The role of FCN2 gene polymorphisms and the level of FCN2 in serum appear to be associated with various bacterial or virus diseases, including mycobacterium tuberculosis, hepatitis virus, and dengue fever." (PMID 39739972, 2024). "Regarding its (patho)physiological role, FCN2 serum levels are induced by the dengue virus infection in humans, are positively correlated with platelet levels, and are negatively correlated with aspartate transaminase (AST)." (PMID 37239116, 2023). "Recently, the association of ficolin-2 levels, along with FCN2 polymorphisms in dengue illness, has been examined." (PMID 34202570, 2021). "Of note, among these PRRs, MBL and ficolin-2 have been the most widely studied in infectious diseases such as dengue." (PMID 34202570, 2021).
lupus nephritis (4 papers, 2018 to 2025). Glomerulonephritis in the context of systemic lupus erythematosus. "Serum ficolin-2 in SLE patients has also been reported to be lower than that healthy controls, and low ficolin-2 levels have been associated with lupus nephritis or thrombocytopenia in patients with SLE." (PMID 32915797, 2020).
pneumonia (4 papers, 2016 to 2024). An acute, acute and chronic, or chronic inflammation focally or diffusely affecting the lung parenchyma, caused by an infection in one or both of the lungs (by bacteria, viruses, fungi, or mycoplasma.). "Recently, we reported for the first time a relationship between SNPs of the FCN2 gene 3′-untranslated region (3′UTR) and very low (≤1500 g) birthweight as well as early onset of infection and pneumonia in preterm newborns." (PMID 36499663, 2022). "Additionally, mice lacking ficolin-A, the murine homolog of FCN2 showed increased mortality in a model of S. pneumoniae pneumonia, suggesting a role for ficolin in S. pnemoniae infection." (PMID 27490795, 2016).